STX2 (syntaxin 2)
Diseases named in the same sentence as STX2 in open-access papers (continued):
Sharing a sentence is not in itself a finding about the gene and the disease.
diarrhoea (10 papers, 2008 to 2024). "As expected, HUS-associated strains carry stx2 and eae genes more frequently than strains causing diarrhoea only (p < 0.01)." (PMID 30806162, 2019). "In fact, stx2 gene alone or associated with stx1 was found only in HUS-associated strains while stx1 as sole stx gene was detected only in the strains recovered from children with diarrhoea." (PMID 29183554, 2017). "Though, none of the isolates harboured a combination of the shiga toxin genes, nonetheless the relatively high occurrence of the stx1 gene (6 %) compared to stx2 (1 %) in the water E. coli isolates suggests the capability of each gene in causing acute diarrhoea in humans." (PMID 26449767, 2015). "Both stx2 and stx2c are mainly hosted by STEC associated with the aetiology of severe human diarrhoea whereas stx2d has been isolated in STEC from human as well as cattle origin." (PMID 29880035, 2018). "Other strains with related Stx2 phages include EHEC O103:H2 str 12009 from a sporadic case of diarrhoea in Japan in 2001, and E. coli O111:H- str 11128." (PMID 22403614, 2012). "Diarrhea-associated E. coli strains encoded virulence factors typical for each of the diarrhea-associated pathotypes including EAggEC (pCVD432), ETEC (lt/st), EIEC (ial/ipaH), EPEC (eaeA/bfpA), EHEC (stx1/stx2/ehly) and DAEC (afaI) strains." (PMID 24774171, 2014). "All five strains in cluster X carried stx1 and stx2, belonged to PT14, and were isolated in 1996 from one HUS case, two contacts of this case and from two individuals with an unspecified disease other than HUS or diarrhoea." (PMID 18366637, 2008).
E. coli infections (7 papers, 2012 to 2025). "This pathology is a complication of Shiga toxin (Stx)-producing Escherichia coli infection and renal damage is attributed to Stx types 1 and 2 (Stx1, Stx2) produced by Escherichia coli O157:H7 and many other STEC serotypes." (PMID 27336788, 2016). "The advent of better diagnositic methods and the availability of a greater arsenal of therapeutic mAbs against Stx2 would greatly enhance treatment outcomes of life threatening E. coli infections." (PMID 24152988, 2013). "In this study, we use the nomenclature proposed in 2009 at the 7th International Symposium on Shiga Toxin-Producing E. coli Infections in Buenos Aires, designating seven Stx2 subtypes as Stx2a, Stx2b, Stx2c, Stx2d, Stx2e, Stx2f, and Stx2g." (PMID 22852065, 2012). "Under Shiga toxin-producing E. coli infection, monocytes may initially bind to Stx2 through TLR4 in the infected intestinal region." (PMID 39871175, 2025). "Although λBH2 phage did not completely repress Stx2 production, these are highly inducing nonphysiological conditions with fecal Stx2 concentrations (∼102 to 103 ng Stx2/g mouse stool) in excess of those encountered in human Stx-producing E. coli infections (∼2 to 50 ng Stx2/ml human stool)." (PMID 31992629, 2020).
gastroenteritis (7 papers, 2013 to 2024). An inflammatory disorder that affects the upper and lower gastrointestinal tract. "Shiga toxins (Stx1 and Stx2) are key virulence factors in the pathogenesis of gastroenteritis, HC and HUS, caused by STEC and other Stx-producing bacteria, including Citrobacter freundii, Enterobacter cloacae, Acinetobacter haemolyticus, Aeromonas sp., and Escherichia albertii." (PMID 29712985, 2018). "Furthermore, EAEC is able to acquire additional virulence genes that could increase its pathogenicity, such as the acquisition of Stx2 phage (a characteristic of enterohemorrhagic E. coli) in a German outbreak of EAEC-associated gastroenteritis." (PMID 28742106, 2017). "In this gastroenteritis outbreak, E. albertii or stx2-positive E. coli O183:H18 was isolated from 24 ill patients; both strains were isolated from 7 patients." (PMID 23260717, 2013). "E. coli O166:H15 has been previously reported causing a gastroenteritis outbreak in 1996 as a non-STEC strain, however the O166:H15 serotype we recovered carried the stx2 gene." (PMID 38814093, 2024).
colorectal cancer (6 papers, 2018 to 2025). A primary or metastatic malignant neoplasm that affects the colon or rectum. "Syntaxin2 (STX2) was associated with colorectal cancer (CRC) invasion and metastasis, as well as poor patient survival." (PMID 32489454, 2020). "A recent report revealed that EXOSC4 interacts with and is regulated by STX2 and promotes the proliferation of colorectal cancer cells." (PMID 35008922, 2022). "Notably, prior research has identified STX2 as a potential therapeutic target and biomarker in colorectal cancer, Building on these findings, this study further elucidates its immunoregulatory role in bladder cancer." (PMID 40755754, 2025). "STX2 is also involved in the progression and metastasis of various cancers, such as mammary adenocarcinoma, hepatocellular carcinoma, ovarian cancer, and colorectal cancer." (PMID 34295885, 2021). "In addition, STX2 has been reported to interact with TRAF6 to activate the NF-κB pathway in colorectal cancer cell lines." (PMID 34295885, 2021).
intestinal infection (6 papers, 2011 to 2023). "Secondly, because STEC/Stx2 is highly endemic in Argentina, it is possible that an asymptomatic or auto-limited gastrointestinal infection with pathogenic strains was insufficient to stimulate a detectable antibody response to Stx2 A subunit." (PMID 21559455, 2011). "Shiga toxin 1 (stx1) and stx2 are the primary virulence factors of Shiga toxin-producing E. coli (STEC) strains, which cause diarrhea post-intestinal infection." (PMID 37019949, 2023). "Oral gavage and intestinal infection with Stx2-producing C. rodentium model of Stx2 provides a reasonable replicate of the time course of human infection with EHEC as well as constant exposure to Stx2 with resultant kidney injury." (PMID 25609181, 2015). "The effect of anti-Stx-1 IgY and anti-Stx-2 IgY on mortality of mice with intestinal infection with GPU993-S and GPU96MM-S was investigated." (PMID 22028896, 2011). "Altogether, the simultaneous release of IL-1β and Stx2-dependent cell death triggered by EHEC strain is a very inflammatory condition that could influence the outcome of intestinal infections." (PMID 31947665, 2020).
kidney damage (6 papers, 2018 to 2025). "The protective effect of CD14 neutralizing antibody treatment on LPS/Stx2-induced mouse kidney damage was validated by PAS (top) and H&E (bottom) staining." (PMID 39871175, 2025). "Plasma urea levels were measured in these mice as a functional parameter of kidney damage and indicator of Stx2 toxicity." (PMID 30513821, 2018). "There is some evidence that neutrophilia directly contributes to Stx2 toxicity as mortality and kidney damage are reduced in a murine model of HUS using polymorphonuclear-cell-(PMN)-depleted mice." (PMID 29988557, 2018). "This study was validated in vivo, by inoculating Balb/c mice with pStx2 and the animals died with typical signs of Stx2 poisoning, including kidney damage, neutrophilia, brain damage, and with detection by immunofluorescence of Stx2 in the brain." (PMID 30274180, 2018).
Encephalopathy (5 papers, 2015 to 2022). Encephalopathy is a term that means brain disease, damage, or malfunction. "Altogether, these results suggest a fundamental role for microglial cells in pro-inflammatory processes in encephalopathies due to Stx2 intoxication and highlight the impact of environmental cues." (PMID 31970091, 2019). "Along the same lines, our group has recently demonstrated in a translational murine model of HUS-derived encephalopathy that systemic sub lethal Stx2 induces MG cell reactivity in the striatum and the hippocampus." (PMID 31970091, 2019). "We postulate that the onset of encephalopathy in STEC infections occurs when Stx-2 attacks vascular endothelial cells of the blood–brain barrier, inducing their death." (PMID 26385393, 2015). "In previous works sub-lethal dose of Stx2 was determined and administered to a characterized murine model of encephalopathy, to mimic and to unravel the cell mechanisms that may occur beyond the clinical signs observed in patients suffering from HUS." (PMID 30732602, 2019). "We hypothesized that MG cells might play a pivotal role in the inflammatory effects of Stx2 observed in the brain and, thus, define the severity of encephalopathies in patients." (PMID 31970091, 2019). "In addition, Shiga toxin 2 (Stx2) targets other organs like the brain, inducing encephalopathies." (PMID 31970091, 2019).
Thrombocytopenia (5 papers, 2012 to 2025). A reduction in the number of circulating thrombocytes. "The count of thrombocytes and leukocytes were not significantly altered in any of the Stx2-challenged groups compared to the corresponding sham groups, suggesting no development of thrombocytopenia or lymphocytopenia in the mice during the experimental period, respectively." (PMID 39062926, 2024).
thrombotic microangiopathy (5 papers, 2017 to 2024). The syndromes of microangiopathic hemolytic anemia, thrombocytopenia, and variable signs of organ impairment, due to platelet aggregation in the microcirculation. "Thrombotic microangiopathy in the kidneys is a hallmark of HUS that was so far only detectable in murine HUS models induced by co-application of Stx2 and LPS." (PMID 29988557, 2018). "Although piglets infected with EHEC O157:H7, including those with neurological signs and brain lesions have thrombotic microangiopathy and other lesions shown to be due to Stx2, these piglets do not have significantly different serum chemistry values that constitute evidence of renal uremia." (PMID 28134751, 2017).
colitis (4 papers, 2011 to 2021). Inflammation of the colon. "This outbreak of colitis caused by STEC serotype O103:H25 (eae and stx2-positive) was characterized by a very high incidence of HUS, and the majority of the affected children experienced severe renal disease and significant extrarenal complications." (PMID 21798000, 2011).
Bovine mastitis (3 papers, 2012 to 2023). INFLAMMATION of the UDDER in cows. "Another study confirmed that the stx2 and eaeA genes were the most prevalent virulence factors in cow's environment that is contaminated by feces, and it is also a frequent cause of bovine mastitis." (PMID 23213293, 2012). "Study in Turkey indicated that genes encoding Shiga toxins 1 and 2 (stx1 and stx2), intimin (eaeA), heat-stable enterotoxin a (Sta), and F5 (K99), F41, and F17 fimbriae were the most prevalent virulence factors which were isolated from clinical bovine mastitis cases." (PMID 23213293, 2012). "Several studies have reported shigatoxin genes (stx1/stx2), and shigatoxigenic E. coli (STEC) are considered the most pathogenic variants in bovine mastitis, although recent studies in Bangladsh and China have reported the absence of stx genes." (PMID 36015067, 2022).
co-infection (3 papers, 2015 to 2020). "In our study, samples from 32.9% (25/76) of STEC cases harbored the stx2 gene (single and co-infection)." (PMID 32708640, 2020).
endothelial dysfunction (3 papers, 2015 to 2022). In vascular diseases, endothelial dysfunction is a systemic pathological state of the endothelium (the inner lining of blood vessels) and can be broadly defined as an imbalance between vasodilating and vasoconstricting substances produced by (or acting on) the endothelium. "While we have made several important observation in the experiments described here promoting a possible role for Stx2-induced DAMPs in the development of endothelial dysfunction underlying HUS, there are still important questions that remain unanswered." (PMID 25904918, 2015). "In conclusion, we described a new pathway of platelet-monocyte interaction, mediated by sCD40L and oxidative stress that may contribute to the progression of endothelial dysfunction during Stx2-associated HUS." (PMID 29068360, 2017). "This suggests that NETs induced in the context of LPS and Stx2 are in part responsible for endothelial dysfunction, but other components might play a role in the global endothelial dysfunction." (PMID 35811684, 2022).
hepatocellular carcinoma (3 papers, 2017 to 2021). A malignant tumor that arises from hepatocytes. "For example, STX2 has been shown to play an essential in human hepatocellular carcinoma invasion and metastasis." (PMID 34295885, 2021).
mastitis (3 papers, 2022 to 2025). Inflammation of breast tissue during lactation or postpartum due to an obstructed duct or infection. "Strikingly, a mastitis isolate was confirmed as the highly virulent E. coli O157:H7 serotype, harboring the Shiga toxin genes stx1 and stx2, underscoring a direct and significant public health risk." (PMID 41148424, 2025). "In chickens, the stx1 and stx2 genes were observed in two isolates (9% for each), whilst isolates from mastitis and diarrhea were free of these genes." (PMID 36836656, 2023). "On the contrary, others had mentioned that E. coli strains isolated from cows with clinical mastitis were negative for both stx1 and stx2 genes." (PMID 35720844, 2022).
bacteremia (2 papers, 2012 to 2023). "Enterohemorrhagic E. coli (EHEC) are not invasive, so bacteremia is rare, but they secrete ribosome inactivating Shiga-like toxins (Stx1 and Stx2 with variants) which are responsible for much of the organ damage, and Stx2 is more frequently associated with severe disease." (PMID 23202315, 2012).
bladder cancer (2 papers, 2018 to 2025). "The results of this study indicate that STX2 is significantly downregulated in bladder cancer tissues, and its expression level is negatively correlated with disease risk, suggesting that STX2 may function as a tumor suppressor gene." (PMID 40755754, 2025). "The bladder carcinoma cell line 5637 was the most sensitive one to Stx1 and Stx2, with IC50 at about 0.028 (Stx1) and 0.007 (Stx2) ng/mL." (PMID 30481169, 2018). "Finally, intersecting these key genes with risk-consistent genes yielded eight immune-related genes that were negatively associated with bladder cancer risk: LIMS2, TP53INP2, IRAK3, STX2, CYP27A1, IL11RA, KCNMB1, and PDLIM7." (PMID 40755754, 2025). "Combined with its role in exosome regulation, STX2 may influence the immune microenvironment of bladder cancer by modulating exosome secretion." (PMID 40755754, 2025). "Subsequent box plot analysis further demonstrated significantly lower expression of six genes (LIMS2, IRAK3, STX2, IL11RA, KCNMB1, and PDLIM7) in bladder cancer cell lines, consistent with bioinformatics analysis." (PMID 40755754, 2025). "Although there are currently no direct clinical interventions targeting STX2, this gene still holds the potential for development as a bladder cancer–related biomarker." (PMID 40755754, 2025). "Through integrated multi-omics analysis and experimental validation, six genes, LIMS2, IRAK3, STX2, IL11RA, KCNMB1, and PDLIM7, were selected as potential immune-related biomarkers for bladder cancer, providing promising biomarkers and therapeutic targets for personalized treatment." (PMID 40755754, 2025). "In vitro qRT-PCR validation in bladder cancer cell lines showed downregulation of LIMS2, IRAK3, STX2, IL11RA, KCNMB1, and PDLIM7, consistent with bioinformatics findings, suggesting that these genes may serve as potential therapeutic targets." (PMID 40755754, 2025). "The consistent downregulation of these genes in bladder cancer tissues was further validated using independent public datasets, and qRT-PCR experiments confirmed the differential expression of the following six genes: LIMS2, IRAK3, STX2, IL11RA, KCNMB1, and PDLIM7." (PMID 40755754, 2025).
diabetes (2 papers, 2022 to 2024). "Several of the diabetes-associated Shigella and Escherichia phages identified, were predicted to possess virulent factors, most notably Shiga toxin genes 1 and 2 (Stx1 and Stx2)." (PMID 39166873, 2024). "Here, we show that Stx2 acts to assist this precise tuning of insulin secretion in β-cells, including in diabetes." (PMID 36316316, 2022). "Furthermore, we showed that targeting the flipping efficiency of Stx2 profoundly modulated insulin secretion, which would benefit restoring the impaired insulin secretion in diabetes." (PMID 36316316, 2022). "Targeting the flipping efficiency of Stx2 profoundly modulates secretion, which could restore the impaired insulin secretion in diabetes." (PMID 36316316, 2022). "Here, we show that modulating PM flipping of Stx2 from inside (inhibitory) to the exterior (relief of inhibition) of the β-cell assists the precise tuning of insulin secretion, and this flipping efficiency can be used to alleviate the impaired insulin secretion in diabetes." (PMID 36316316, 2022).
acute pancreatitis (1 paper, 2022). An acute inflammatory process that leads to necrosis of the pancreatic parenchyma. "An interesting mechanism, reported recently by H. Gaisano’s laboratory, involves the depletion of Syntaxin 2 (STX-2) in the experimental acute pancreatitis." (PMID 36010591, 2022). "The depletion of STX-2 (in STX-2 KO mice) increased the binding of ATG16L1 to clathrin with the consequent impairment of autophagic flux and increased severity of experimental acute pancreatitis." (PMID 36010591, 2022).
Alzheimer disease (1 paper, 2021). A progressive, neurodegenerative disease characterized by loss of function and death of nerve cells in several areas of the brain leading to loss of cognitive function such as memory and language. "Many of the SNARE complex genes involved in presynaptic vesicle exocytosis were significantly downregulated in Alzheimer’s disease, including SNAP-25, STX1A, SYT1 and VAMP2, while STX2, SYN1 and VAMP3 were not changed." (PMID 34423299, 2021).
Blindness (1 paper, 2017). Blindness is the condition of lacking visual perception defined as a profound reduction in visual perception. "In conclusion, our data support the model of Stx1 or Stx2-induced apoptosis and ER stress pathways in human retinal pigment epithelial cells, suggesting the ocular involvement of Stxs in the pathogenesis of disease leading to visual impairment or blindness." (PMID 29027919, 2017).
brain infarcts (1 paper, 2017). "The amount of Stx2 produced by the strain was correlated with a reduction in survival, manifestation of CNS signs, and brain infarcts." (PMID 28134751, 2017).
breast carcinoma (1 paper, 2021). "For example, overexpression of STX2 can facilitate the carcinogenesis of mice breast cancer by increasing C/EBPβ, keratin-14, matrix metalloproteinase-3 (MMP-3), and β-catenin expression." (PMID 33754003, 2021).
colon cancer (1 paper, 2021). "Stx2 itself appears to be sufficient to stimulate F3 expression in epithelial cells because we found that addition of exogenous Stx2 to tissue cultured HT29 cells, a human colon cancer cell line, induced expression of F3 transcripts to similar levels observed with WT EHEC infection." (PMID 33529199, 2021).
colorectal tumors (1 paper, 2018). "We detected STX2 mRNA expression in 55 primary colorectal tumors and paired adjacent normal tissues using qPCR." (PMID 29855462, 2018).
enteritis (1 paper, 2018). Inflammation of the small intestine. "An extended time requirement for leukocytes to express potential receptors for carrying Stx2 following exposure to inflammatory conditions is consistent with the “window period” between the debut of severe enteritis attributable to STEC and the emergence of HUS in the clinic." (PMID 29507316, 2018).
glomerular disease (1 paper, 2020). "Since STEC-HUS is mainly a glomerular disease we assessed HO-1 expression in HGMVECs with co-stimulation of Stx2 and heme." (PMID 33414780, 2020).
glucosuria (1 paper, 2022). "Indeed, we observed glucosuria in Stx2-injected mice that reproduces other study with Stx1-injected mice indicating SGLT1 (SLC5A1) dysfunction in the proximal tubules." (PMID 35202097, 2022).